ENSG00000293584 (novel protein)
Safety:
Unwanted effects reported when the protein is acted on. In parentheses: how it was acted on, where the effect was seen, and who reports it.
osteonecrosis (source: ClinPGx)
osteonecrosis when treated with corticosteroids (source: ClinPGx)
Gene: Protein-coding gene on chromosome 2 (111,121,153 to 111,123,765, forward strand). Ensembl gene ENSG00000293584.